IL6 (interleukin 6)
Diseases named in the same sentence as IL6 in open-access papers (continued):
Sharing a sentence is not in itself a finding about the gene and the disease.
COVID-19 (continued). "PPI network and core target analysis indicated that IL-6, TNF, MAPK1, and IL1B were the key targets against COVID-19." (PMID 38018195, 2023). "Anti-inflammatory agents such as corticosteroids, NSAIDs, monoclonal antibodies against as IL-6 (Tocilizumab), IL-1 (Canakinumab), and TNF-α (Adalimumab and Golimumab), and Interferon-based immunotherapy can be applied to treat COVID-19 patients." (PMID 37365605, 2023). "Recent studies show, in addition to wellknown factors such as IL-6, CRP, and ferritin, the NLR is also a valuable predictive factor for severe COVID-19." (PMID 37814623, 2023). "Baricitinib is currently used in COVID-19 treatment, this is a selective JAK inhibitor (JAK1 and JAK2) that has shown to indirectly decrease IL-6 production." (PMID 36941580, 2023). "Age, congestive heart failure, obesity, COPD, prior stroke, and increased concentration of urea, LDH, CRP, IL-6, troponin I, ALT to AST ratio were identified to be the predictors for in-hospital mortality of COVID-19 patients." (PMID 37624796, 2023). "The dysregulated inflammatory responses measured using plasma cytokine concentrations appear different between COVID-19 and CAP, with COVID-19 patients showing higher levels of IP-10, IL-10, and IL-6, and CAP patients had higher levels of GM-CSF." (PMID 36814234, 2023). "We found that monocytes from convalescent COVID-19 patients expressed significantly lower levels of both TNF-α and IL-6 in response to LPS stimulation, consistent with our findings regarding the expression of activation markers and cellular CD142." (PMID 38250080, 2023). "High levels of inflammatory mediators, such as IL-6, CRP, and neutrophil, have been reported in COVID-19 patients, and this reflects acute inflammatory responses related to cytokine storms." (PMID 37896957, 2023). "Cytokine ratios, such as high IL-6:A1AT levels, are related to worse prognosis in COVID-19 patients." (PMID 36831051, 2023). "Data revealed the expected increasing effect of COVID-19 for ALT, GGT, LDH, ferritin, and CRP in the deceased group and for IL-6 in the ICU individuals." (PMID 36831321, 2023). "The impaired inflammatory response in COVID-19 patients may be due to a singular low expression of type I and III IFNs, resulting in reduction of antiviral defense, associated with elevated NF-kB-induced chemokines, leading to leukocytes recruitment and high expression of proinflammatory IL-6." (PMID 37371134, 2023). "Even though our findings resulted from a monocentric study and the time frame for patient enrollment was limited, they highlighted the pivotal role of IL-6, LDH, CRP and PCT in predicting mortality for hospitalized COVID-19 patients." (PMID 36836679, 2023). "COVID-19 patients with AKI, ARDS, low oxygen saturation and thrombocytopenia had the highest levels of IL-6 (p 0.05)." (PMID 37889917, 2023). "Among these cytokines, levels of IL-1β, IL-6 and TNF-α were also significantly elevated in individuals with ongoing post-acute sequelae of COVID-19, and they were positively correlated with each other." (PMID 37674675, 2023). "Macrophages that contained SARS-CoV-2 viral particles were found to express IL-6, while CD14+ and CD16+ monocytes, which specifically produce IL-6, were observed in the peripheral blood of patients with severe COVID-19." (PMID 37892134, 2023). "This study aimed to evaluate the differences in IL-6 level and the NLR in mild and severe COVID-19 and assess their correlation with COVID-19 severity and the correlation of IL-6 and NLR in COVID-19." (PMID 38099004, 2023). "Few studies in the Eastern Mediterranean Region reported higher serum levels of IL-1β, IL-6, IL-8, and TNF in severe COVID-19 patients compared to mild cases." (PMID 37228441, 2023). "The PPI network revealed that IL-6, MAPK1, TNF, and IL1B were the main targets of bitter almond-licorice to interfere with COVID-19." (PMID 38018195, 2023).
COVID-19 (continued). "A longitudinal increase in a variety of inflammatory cytokines, including IL6, IL8/CXCL8, and TNFA, in COVID-19 patients has been observed." (PMID 36798115, 2023). "MVPA also modulated the peripheral frequency of Treg cells and the expression of PD-1 in CD8+ T cells, although it abrogated the statistical effect in the analysis of TNF-α and IL-6 production by LPS- and PMA-stimulated PBMC of post- COVID-19 patients." (PMID 37753077, 2023). "According to current findings, extremely ill COVID-19 patients, like those with ARDS, have higher levels of pro-inflammatory cytokines like interleukin 6 (IL-6), in their serum." (PMID 37365605, 2023). "Also, Tregs has been previously found in a low percentage due to the proinflammatory cascade driven by IL-6, which could be diminished in recovered COVID-19 patients and may boost the levels of Tregs, as observed in the discharged COVID-19 patients after one week of follow-up." (PMID 38035104, 2023). "The secretion of cytokines and chemokines, including IL6, CXCL8, IL1B, IL10 and CCL2, is significantly increased in COVID-19 AKI." (PMID 37274117, 2023). "The aim of this study was to investigate the predictive utility of interleukin (IL)-6, IL-8, IL-10, IL-12, tumor necrosis factor alpha (TNF-α), and interferon gamma (IFN-γ) measurement in patients with COVID-19." (PMID 37969879, 2023). "Here, we found that post-COVID-19 patients presented higher systemic levels of PGE2, TNFRSF-1a, and IFN-α concomitantly to lower IL-6 concentrations." (PMID 37753077, 2023). "To that end, we conducted ELISA-based measurements of the levels of Ang1, Ang2, IL-6, as well as titers of IgG against the spike protein RBD, in the serum samples of hospitalized COVID-19 patients with various degrees of disease severity." (PMID 38138084, 2023). "This study highlighted the significance of biomarkers WBC count, MPV, PWD, platelet count, NLR, serum ferritin, D-dimer, CRP, IL-6, LDH, and PCT levels in predicting the severity of COVID-19 patients." (PMID 37016651, 2023). "However, lack of B cells has been associated with a mild form of COVID-19 suggesting that inflammatory cytokines, especially IL-6, may have a central role in the disease severity." (PMID 37711609, 2023). "In addition, we showed that the cytokines IFN-γ, IL-2, IP-10, IL-1β, IL-6, IL-8, and TNF could discriminate the status of SARS-CoV-2 infection or exposition, and also it highlighted the high levels of pro-inflammatory IL-1β and IL-6 in long-COVID-19 when compared to the unexposed group." (PMID 37018291, 2023). "In patients with COVID-19, anti-Spike and anti-RBD IgA levels were positively correlated with the inflammatory cytokine IL-6." (PMID 37876932, 2023). "Sarilumab, another IL-6 inhibitor, was studied in the REMAP-CAP study and showed benefits in severe COVID-19 patients." (PMID 37065291, 2023). "The biochemical indices of inflammation include C-reactive protein (CRP), D-dimer, serum ferritin, hemoglobin (Hb), interleukin-6 (IL-6), lactate dehydrogenase (LDH), which are routinely done in COVID-19 patients admitted in AIIMS Patna." (PMID 37016651, 2023). "A recent study reported that alveolar macrophages activated by COVID-19 through TLR signaling produced interleukin-1 (IL-1), which further stimulates mast cells to produce interleukin-6 (IL-6)." (PMID 37686069, 2023). "Conclusions: at the admission stage, IL-6 and SAA are useful markers for COVID-19 patients with CKD." (PMID 38203482, 2023). "Individuals with severe and fatal COVID-19 displayed neutrophilia and lymphopenia, as well as increased levels of CRP, ferritin, and cytokines such as IL-6, IL-10, gamma interferon (IFN-γ) and TNF-α." (PMID 36852984, 2023). "Among 48 cytokines/chemokines, evaluated by multiplex analysis in patient plasma, 6 (IL-6, CXCL-10, HGF, MIG, MCP-1, and G-CSF) were identified as highly significant in COVID-19 patients compared to non-COVID-19 respiratory disease controls (p-value < 0.0001)." (PMID 37685858, 2023).
COVID-19 (continued). "In COVID-19 patients, SGLT2-inhibitor canagliflozin showed a reduction in interleukin-6 (IL-6) levels, which are crucial in triggering cytokine release syndrome (CRS)." (PMID 36839456, 2023). "Serum semaphorin levels show better predictive values than CRP, IL-6 and LDH for differentiating critical from moderate/severe COVID-19." (PMID 37893159, 2023). "Severe manifestations of COVID-19 may be partly accounted for by an autoimmune reaction mediated by a dysregulated network of circulating proinflammatory cytokines and inflammatory markers, including IL-1β, IL-6, IL-2, IL-8, IL-17, TNF-α, C-reactive protein, D-dimer, and antibodies." (PMID 37712090, 2023). "The levels of IFN-γ, IL-1Ra, IL-6, and MCP-1 were elevated in male patients with severe COVID-19, while those of TNF-α were high in COVID-19 female patients." (PMID 37896963, 2023). "The COVID-19 group had significantly higher levels of IFN-γ (P<0.01), IL-2 (P<0.01), IP-10 (P<0.01), IL-1β (P = 0.001), IL-6 (P = 0.002), IL-8 (P = 0.003), and TNF (P = 0.014) when compared to the unexposed healthy group." (PMID 37018291, 2023). "A recent study revealed that COVID-19 patients have elevated levels of biomarkers such as CRP, LDH, and IL-6 in case of extreme cytokine storm syndrome." (PMID 36671484, 2023). "Following treatment with Allocetra–OTS, most of these inflammatory immune-modulators, including IL-6, IFN-γ, IL-10, TNFR1, IP-10, MCP-3, and IL-7, gradually decreased to normal levels with resolution of COVID-19." (PMID 37600829, 2023). "For the first time, this study evaluated IL-6 in a broad collective of respiratory patients—from upper respiratory tract infection to pneumonia to sepsis with ARDS—including COVID-19 and non-COVID-19 regarding the degree of lung infiltrates." (PMID 37733154, 2023). "Overall, higher serum IL-1 β, IL-6, and TNF-α levels were reported in COVID-19 compared to periodontitis." (PMID 37106750, 2023). "Interleukin-6 (IL-6) receptor blockers and Janus kinase (JAK) inhibitors are the most important immunotherapies for COVID-19." (PMID 38264533, 2023). "Increased levels of IL-6 and C-reactive protein (CRP) have been found in blood samples from COVID-19 patients with peak levels measured at 3 days after hospitalization in critically ill survivors and a continuous increase in non-survivors." (PMID 37168848, 2023). "Blood specimens were collected and indicate several laboratory features of severe COVID-19, such as increased C-reactive protein (CRP) and interleukin-6 (IL-6)." (PMID 37417740, 2023). "Our study reaffirms previous studies reporting increased IL-6, CXCL10 and IL-16 serum levels in patients with COVID-19 with BSI being a major bias." (PMID 36759861, 2023). "For example, increased IL-5, IL-6, IL-10, and MIG but deceased MIP-1β were observed in patients with severe/critical COVID-19 or those admitted to ICU, with satisfactory AUCs for predictive performance." (PMID 37469595, 2023). "COVID-19 patients and those with liver injury exhibit clinical manifestations, including elevation in ALT, AST, GGT, bilirubin, TNF-α, and IL-6 and reduction in the levels of CD4 and CD8." (PMID 36671484, 2023). "Patients in this second phase with severe COVID-19 often present with elevated D-dimer, C-reactive protein (CRP), IL-6, acute kidney injury, and heightened complement deposition." (PMID 37398192, 2023). "Furthermore, targeting the hyper-inflammatory response in patients with severe COVID-19, we prepared a complete set of cytokine antibodies, such as anti–IL-6, anti–IL-8, anti–IL-10, anti–TNF-α, and anti-MCAF, which could stop inflammatory damage, and anti–TGF-β which prevent pulmonary fibrosis." (PMID 36960050, 2023). "In patients with severe COVID-19 and poor outcomes, the lymphocyte, eosinophil and platelet counts decreased, whereas neutrophil, NLR, IL-6, procalcitonin, D-dimer, ferritin, amyloid A protein and CRP levels increased." (PMID 38099004, 2023).
COVID-19 (continued). "Serum levels of IL-6, ferritin, ESR, CRP, D-dimer and fibrinogen are significantly higher, as COVID-19 is an inflammatory and prothrombotic state." (PMID 36984473, 2023). "Here, we detected increased expression of IL-6 and TGF-β by EVs obtained from COVID-19 patients, which is in agreement with previous results obtained from peripheral blood." (PMID 37251406, 2023). "DPP3, IL-6, CRP, and leucocytes were significantly elevated in COVID-19 patients with infiltrate above the median compared to patients with infiltrate below the median (each p < 0.05) and outpatients without imaging (each p < 0.05)." (PMID 37733154, 2023). "As expected, the plasma concentrations of proinflammatory cytokines IFN-γ, IL-6, IL-8, MCP-1, macrophage inflammatory protein (MIP)-1α, MIP-1β and TNF-α were elevated in COVID-19 subjects." (PMID 37205106, 2023). "Various therapeutic targets have been reported for COVID-19, including spike protein (S-RBD), IL-6, ACE-2, and COVID-19 main protease (MPro)." (PMID 37049752, 2023). "In addition, some inflammatory factors such as IL-6 play an important role in both ADs and cytokine storms, so the relationship between the activation of inflammatory responses and ADs in COVID-19 for cytokine storms generated by the organism may be one of the hotspots." (PMID 37395896, 2023). "They identified drugs targeting IL-1β, IL6, IL-6Rα, and TNF-α, as well as corticosteroids, through interactome mapping between COVID-19-related proteins and their known drug targets according to current therapeutic approaches." (PMID 37631998, 2023). "The receiver operating characteristic curve found age, urea, uric acid, CRP, ferritin, IL6, and LDH with the highest odds of predicting ICU admission for COVID-19 patients." (PMID 36819455, 2023). "Our result also showed significantly higher levels of IL-6 and IFN-γ were observed in COVID-19 patients than in HC subjects." (PMID 36810114, 2023). "In both groups, IL-6 was significantly correlated with CRP (COVID-19: ρ = 0.73, p < 0.001; non-COVID-19: ρ = 0.70, p < 0.001) and leucocytes (COVID-19: ρ = 0.39, p < 0.001; non-COVID-19: ρ = 0.57, p < 0.001)." (PMID 37733154, 2023). "In this context, our results show a statistically significant increase in the expression levels of IL-6, CRP, IDO1 and ACE2 in patients with severe disease compared to patients with mild and moderate COVID-19." (PMID 37715121, 2023). "Our data confirm a reduction in the respiratory index PO2/FiO2 and a concomitant increase in IL-6 and CRP levels, a peculiar consequence of the cytokine storm, which are significative indicators for severe COVID-19." (PMID 37631910, 2023). "This means that the body avoids a prolonged inflammatory response and its damaging effects since it is known that there is increased expression of pro-inflammatory cytokines IL–1β, IL–6, TNF, IL–12, IFN–β, IFN–γ, IL–17 in COVID-19." (PMID 36833234, 2023). "An analysis was performed to evaluate any correlations between the biomarkers (IL-6 and SAA) and the frequency of AKI in each COVID-19 group." (PMID 38203482, 2023). "Current clinical guidelines for treating COVID-19 with ARDS is triple therapy: remdesivir, tocilizumab (anti-IL-6 monoclonal antibody), and corticosteroid." (PMID 36914565, 2023). "As VD has been shown to have immunomodulatory activity on IL-6, and anti-IL-6 agents have already demonstrated a role in the course of COVID-19, it has been speculated that administration of VD supplementation could be beneficial in terms of COVID-19 progression." (PMID 36983830, 2023). "Adrenocortical hormones and various immunomodulators play a role in the management of COVID-19, including Janus-kinase/signal transducers and activators of transcription (JAK-STAT) inhibitors, IL-6 inhibitors, and IL-1 receptor blockers." (PMID 38050265, 2023).
COVID-19 (continued). "The aim of this study was to evaluate a COVID-19 vaccine allergy using in vitro T-cell exposure to the tested drug with the flow cytometry measurement of CD69, CD40L, TNFa, IFNG, IL-2, IL-4, IL-6, IL-10, intracellular granulysin, and IFNgamma." (PMID 37686102, 2023). "The current study provides evidence that supplementation with HydroCurc improves inflammatory profiles, specifically levels of IL-6 and MCP-1, in adults who had previously tested positive for COVID-19 and were subsequently vaccinated." (PMID 37049389, 2023). "Severe patients (n = 6) showed a significant increase in a subset of plasma cytokine/chemokine levels (IL-2, IL-4, IL-6, IL-8, MIP-1β, and TNF-α; ANOVA, p adjusted <0.05 to <0.001) in comparison with the pauci COVID-19 patients (n = 8) and/or controls." (PMID 37047752, 2023). "The marked increase in COVID-19 disease severity is a result of neutrophil migration and G-CSF, TNF-a, IL-1b and IL-6 activation." (PMID 37091818, 2023). "In this regard, it has been suggested that activation of PPARγ during COVID-19 can reduce the circulating levels of TNF-α, IL-1, and IL-6 in the innate immune cells such as macrophages and monocytes through interaction with NF-κB." (PMID 36875108, 2023). "First, we measured plasma levels of 8 cytokines (IFN-α, IL-1α, IL-1β, IL-10, IL-6, IL-8, S100A8/A9 (calprotectin), and TNF-α), which were shown to be upregulated in the blood of severe COVID-19 patients." (PMID 38082066, 2023). "The top 10 of 41 potential anti-COVID-19 core targets (AKT1, TNF, HSP90AA1, IL-6, mTOR, EGFR, CASP3, HIF1A, MAPK3, and MAPK1) were identified as molecular targets of key active phytonutrients of the Meliae cortex that might be implicated in ameliorating COVID-19." (PMID 36817449, 2023). "This work was performed to identify possible COVID-19 prognostic markers with special concern for ACE-2 and IFITM-3 genetic variations and IL-6 level assays." (PMID 38155729, 2023). "Another study demonstrated that the levels of several cytokines (e.g., IL-6, IL-10, and MCP-1) positively correlated with COVID-19 severity; moreover, MCP-1 was correlated with days on mechanical ventilation." (PMID 37081872, 2023). "Dexamethasone, by targeting the glucocorticoid receptor is able to modulate COVID-19-evoked ARDS through pathways with wide effects on inflammatory factors, such as NF-κB, IL-1β, TNFα and IL-6, as well as fibrosis." (PMID 36791125, 2023). "The worsening clinical state in COVID-19 is related to the elevation of pro-inflammatory cytokines, such as TNF-α and IL-6, in a condition known as cytokine storm." (PMID 37686837, 2023). "In the 2nd pregnancy trimester, increased ratios were observed for IL-6, IFN-γ, IL-5 and GM-CSF (3x increase) in the COVID-19 group." (PMID 37122732, 2023). "Ongoing research on IL-6 and NLR in COVID-19 reveals a correlation between IL-6 and NLR with COVID-19 severity." (PMID 38099004, 2023). "It has been shown that COVID-19 patients present with elevated levels of soluble thrombomodulin, von Willebrand Factor (VWF), and proinflammatory IL-6, all indicative of procoagulant endothelial phenotype, i.e., endotheliopathy." (PMID 36634048, 2023). "Altered levels of proinflammatory cytokines IL-1β, IL-6, and TNFα, in addition to type II IFNγ and also types I and III IFNs, are seen in individuals recovered from COVID-19 compared to those with severe disease." (PMID 37364688, 2023). "While there were also findings of high interleukin 6 (IL-6), lactate dehydrogenase (LDH), high blood sugar, and gamma-glutamyl transferase (GGT) in more severe COVID-19 patients." (PMID 37235308, 2023). "Altogether, these findings show that some parameters such as IL-6, IL-8, type I IFNs, CRP, neutrophil and platelet counts presented significant differences in patients with severe COVID-19 with different clinical outcomes (deceased versus discharged)." (PMID 36817433, 2023).